CELF1 (CUGBP Elav-like family member 1)
Diseases named in the same sentence as CELF1 in open-access papers (continued):
Sharing a sentence is not in itself a finding about the gene and the disease.
nasopharyngeal carcinoma (2 papers, 2022 to 2023). A carcinoma arising from the nasopharyngeal epithelium. "Sp1-induced AFAP1-AS1 contributes to proliferation and invasion by regulating the miR-497-5p/CELF1 pathway in nasopharyngeal carcinoma." (PMID 35034634, 2022). "Only research in nasopharyngeal carcinoma had described that SP1 induced AFAP1-AS1, which could promote nasopharyngeal carcinoma progression by miR-497-5p/CUGBP Elav-like family member 1 (CELF1)." (PMID 37686205, 2023).
type 2 diabetes (2 papers, 2024 to 2025). "Additionally, upregulated CELF1 contributes to the mis-splicing of several genes, including those encoding chloride channels, sodium channels, and the insulin receptor, which are linked to key clinical symptoms of myotonia and type 2 diabetes mellitus (T2DM)." (PMID 41303475, 2025). "The findings suggest that CELF1 plays a pivotal role for in the regulation of type 2 diabetes, indicating that targeting CELF1 may hold promise as a prospective therapeutic approach for combating to type 2 diabetes." (PMID 38443798, 2024).
adenocarcinoma of the breast (1 paper, 2017). "CELF1 has been found involved in previous fusions with five different partners: with MTCH2 and MYOM1 in SCC and adenocarcinoma of the lung, respectively; with LUZP2 and ARFGAP2 in adenocarcinoma of the breast; and with BBOX1 in grade I-II astrocytoma of the brain." (PMID 28186972, 2017).
chronic myeloid leukemia (1 paper, 2016). "In chronic myeloid leukemia, CELF1 is repressed, resulting in a decrease of C/EBPβ isoforms, particularly LAP2." (PMID 27485439, 2016).
colon cancer (1 paper, 2022). "Our findings indicated that DEDD2, GTF2H5, SNRPA1, BICD1, CELF1, and CLK3 were prognostic risk factors for colon cancer, while ADAD1, CMTR1, HNRNPUL1, FTSJ3, WDR43, THUMPD3, SNRPF were prognostic protective factors." (PMID 36212157, 2022).
diffuse large B-cell lymphoma (1 paper, 2017). "Positive correlations between CELF1 and DEK mRNA expression in uveal melanoma and ten additional tumor types (including diffuse large B cell lymphoma, thyroid carcinoma or prostate adenocarcinoma) further reinforce the translational relevance of our results." (PMID 29269732, 2017).
Fanconi anemia (1 paper, 2012). Fanconi anemia (FA) is a hereditary DNA repair disorder characterized by progressive pancytopenia with bone marrow failure, variable congenital malformations and predisposition to develop hematological or solid tumors. "In RNA-seq data, TNF receptor-associated factor 1 (TRAF1) was upregulated by 7.96 fold; CUGBP, Elav-like family member 1 (CELF1) was down-regulated by 1.16 fold; and Fanconi anemia, complementation group D2 (FANCD2) was down-regulated by 1.70 fold." (PMID 22359579, 2012).
gastric cancer (1 paper, 2024). A primary or metastatic malignant neoplasm involving the stomach. "The findings underscore the essential role of CELF1 in gastric cancer cell proliferation, highlighting the potential of RNA interference-mediated CELF1 silencing as a promising therapeutic strategy for gastric cancer." (PMID 38443798, 2024).
liver cancer (1 paper, 2024). An epithelial or non-epithelial malignant neoplasm that arises from the liver. "The impact of the CELF1 phosphorylation state on its stability/degradation has been shown in both DM1 models and models of liver cancer." (PMID 39343007, 2024).
male infertility (1 paper, 2024). The inability of the male to effect fertilization of an ovum after a specified period of unprotected intercourse. "Targeted disruption of CELF1 impairs spermatogenesis, causing male infertility." (PMID 38982349, 2024).
ovarian carcinoma (1 paper, 2018). A malignant neoplasm originating from the surface ovarian epithelium. "In addition, CELF1 has been associated with certain types of cancer, and expression of ABCA7 significantly increased in ovarian carcinoma." (PMID 29723294, 2018).
renal fibrosis (1 paper, 2024). A final common manifestation of a wide variety of chronic kidney diseases characterized by glomerulosclerosis and tubulointerstitial fibrosis. "This compound achieves its inhibitory effect on renal fibroblast activation by downregulating CELF1 expression, offering a promising therapeutic approach for alleviating renal fibrosis." (PMID 38443798, 2024). "Therefore, targeting the suppression of CELF1 expression emerges as a prospective strategy for mitigating renal fibrosis." (PMID 38443798, 2024).
cancer (34 papers, 2011 to 2026). A tumor composed of atypical neoplastic, often pleomorphic cells that invade other tissues. "Conversely, downregulation of CELF1 has been found to alleviate deficiencies in transcriptional inhibition and plays a significant role in various cancer types." (PMID 38443798, 2024). "CELF1 can regulate alternative splicing patterns in various genes associated with cancer." (PMID 41306913, 2025). "Furthermore, while previous studies have mainly focused on the association between CELF1 and cancer, the more precise and in-depth biological functions of CELF1 have been less explored." (PMID 38443798, 2024). "CELF1 expression is found to increase proliferation and progression of several cancers, whereas increased CELF1 could cause G1 phase growth arrest in intestinal epithelial cells, suggesting its diverse role in carcinogenesis." (PMID 34788230, 2021). "Network analysis found a strong association between CELF1 and cell cycle, consistent with previous studies linking CELF1 to cell cycle regulation and proliferation during skeletal muscle differentiation, T cell activation, oocyte maturation, and cancer." (PMID 26866591, 2016). "Firstly, we conducted a pan-cancer analysis of CELF1 expression using TCGA data, revealing significantly elevated levels of CELF1 across various tumors, with the most notable difference observed in AML." (PMID 40781108, 2025). "These particular genes display diminished importance in cancer cell lines included in the Cancer Cell Line Encyclopedia (CCLE) that exhibit overexpression of CELF1." (PMID 41306913, 2025). "This implies that cancer cell lines within the CCLE dataset, manifesting high CELF1 levels, possess an enhanced capacity to regulate metabolism across various cancer types." (PMID 41306913, 2025). "Emerging evidence suggests that CELF1 dysregulation can influence crucial molecular processes involved in cancer pathogenesis." (PMID 41306913, 2025). "Dysregulation of CELF1 can affect the expressions of these genes, leading to uncontrolled cell growth and reduced cell death, which are characteristic features of cancer." (PMID 41306913, 2025). "CELF1 has been shown to play a role in regulating the onset and progression of several cancers affecting different organs, including the oral cavity, liver, lung, and intestine." (PMID 38443798, 2024). "Although there is still a long way to go in the study and application of CELF1 inhibitors, further understanding of CELF1's mechanisms and inhibitors is necessary due to its rich network of targeted effects in multiple cancers." (PMID 38443798, 2024). "CELF1 has been found to be upregulated across various cancer types, and extensive investigations have revealed the mechanisms through which CELF1 operates in the context of cancer." (PMID 38443798, 2024). "In the majority of cancers, CELF1 promotes cancer cell proliferation, metastasis, and invasion by activating downstream pathways including AKT/ERK and ETS2." (PMID 38443798, 2024). "Previous studies have shown that CELF1 is an attractive target for the development of novel molecular-targeted cancer therapies." (PMID 38443798, 2024). "Understanding the role of CELF1 in cancer development and its interaction with signaling pathways provides valuable insights into potential therapeutic strategies for cancer treatment." (PMID 38443798, 2024). "The downregulation of CELF1 can disrupt these signaling cascades and potentially impede the progression of cancer." (PMID 38443798, 2024). "In nasopharyngeal carcinoma, LncRNA AFAP1-AS1 can enhance cancer growth by affecting the miR-497-5p/CELF1 axis." (PMID 34681716, 2021). "To explore the effects of miR-491-5p on the progression of cancer with high level of circ_CELF1, we transfected miR-491-5p into circ_CELF1-expressing NSCLC cells." (PMID 34788230, 2021).
cancer (continued). "To investigate the status of circ_CELF1 in the development of NSCLC, we employed qRT-PCR and found that the mRNA level of circ_CELF1 was significantly increased in primary cancer tissues as relative to their adjacent normal tissues." (PMID 34788230, 2021). "Results: circ_CELF1 is upregulated in primary cancer tissues from patients with NSCLC, and a high level of circ_CELF1, is associated with malignant characteristics and poor outcomes of patients with NSCLC." (PMID 34788230, 2021). "Depletion of CELF1 results in growth inhibition, decreased cell viability, and apoptosis in mice and several cancer cells." (PMID 31534127, 2019). "A transposon-based genetic screen in mice identified CELF1 as a potent cancer driver in colorectal cancer." (PMID 31534127, 2019). "CELF1 has been reported to promote the expression of pro-tumourigenic genes and to be a critical regulator of cancer biological processes, such as proliferation, cell survival, and epithelial-mesenchymal transition (EMT)." (PMID 31443305, 2019). "Although increased levels of CELF1 protein expression were noted in carcinomas derived from 15 of the 20 organ types, this was observed in only a low proportion (ranging from 5–20%) of specimens." (PMID 27869122, 2016). "Nuclear CELF1 is well characterized for its role in alternative pre-mRNA splicing in a variety of model systems; however, its role in pre-mRNA splicing in cancer is understudied." (PMID 26498364, 2015). "Our approaches identified 1283 mRNAs differentially regulated as a function of CELF1 expression and more importantly CELF1 promoted alternative splicing of several target pre-mRNAs, which are known to be involved in various cancer biological processes." (PMID 26498364, 2015). "The RNA binding protein CELF1 (also known as CUGBP1) is emerging as a critical regulator of cancer cell proliferation and apoptosis." (PMID 26498364, 2015). "CELF1 is known to regulate cancer cell apoptosis hence, we sought to determine if CELF1 expression would protect OHKC-CELF1 cells against environmental stress induced cell death." (PMID 26498364, 2015). "The CELF1 siRNA method has emerged as a potentially powerful tool for cancer therapeutics in silencing genes responsible for cancer progression and tumorigenesis." (PMID 24237593, 2013). "It is worth highlighting that research is currently delving into the specific ways in which CELF1 is involved in driving cancer development and progression, and the specific roles of CELF1 may vary depending on the cancer type and context." (PMID 41306913, 2025). "In conclusion, CELF1 holds great research potential as a potential target in cancer." (PMID 38443798, 2024). "Furthermore, simultaneous efforts should be made to further elucidate the specific biological functions of CELF1 in order to advance precise treatments for CELF1-driven cancers in the clinical setting." (PMID 38443798, 2024). "Multiple studies have suggested that CELF1 is a potential therapeutic target in cancer." (PMID 38443798, 2024). "Although there have been numerous reports on the role of CELF1 in cancer progression and development, further research is still needed to construct a more precise CELF1-targeted regulatory network and explore its functions in various types of cancer." (PMID 38443798, 2024). "easyCLIP was then used to generate data for 11 additional known RBPs, chosen as representatives (FBL, which associates with C/D-box small nucleolar RNA (snoRNA), and other noncoding RNA (ncRNA), hnRNP C), at random (CELF1, hnRNP D), or for their relevance to cancer (the others)." (PMID 33692367, 2021). "CELF1 is a potent cancer driver whereas CELF2 is potential tumor suppressor." (PMID 31534127, 2019). "CELF1 is a critical regulator of cancer cell proliferation and apoptosis." (PMID 31159745, 2019). "CELF1 expression levels were higher in low-grade cancers compared with high-grade cancers." (PMID 24237593, 2013).
cancer (continued). "As a member of the RNA-binding protein family, increasing evidence supports CELF1 as a key regulatory factor in transcriptional regulation, mRNA splicing, cell proliferation, and cell cycle progression, playing important roles in maintaining homeostasis, development, and cancer." (PMID 38443798, 2024). "Finally, to determine whether misexpression of CELF1 protein may occur in other cancer types, we compared CELF1 expression between carcinomas and normal tissue controls of 20 distinct organs on a high-density tissue array." (PMID 27869122, 2016). "This review explores how specific RBPs, such as LIN28, IGF2BPs, Musashi, HuR, and CELF1, contribute to CRC by affecting the stability and translation of key cancer-related genes." (PMID 39456596, 2024). "Conversely, MTA2, DDX46, CDCP1, and CELF1, which have been reported to play a role in at least one of these processes in CRC, are known to promote cancer." (PMID 37510319, 2023). "To explore the effects of circ_CELF1 expression on cancer resistance to immunotherapy, we assessed the anti-tumor effects of the PD-1 antibody in C57BL/6 mice bearing circ_CELF1-expressing or circ_NC-expressing cells." (PMID 34788230, 2021). "A higher expression level of CELF1 was observed in patients with the increase of T stage, indicating that when tumors begin to grow larger, gradually some other mechanism(s) may play a more important role to promote cancer cell growth, so the CELF1 expression level had some decrease." (PMID 24237593, 2013). "This discrepancy likely stems from the following: (i) methodological differences (subtype-stratified IHC vs. pan-cancer mRNA sequencing) and (ii) post-transcriptional regulation by ELAVL1, which stabilizes CELF1 protein in aggressive subtypes, as observed in oral SCCs." (PMID 41306913, 2025). "To investigate this possibility, we intersected the genes whose AS was affected by apigenin with experimentally validated substrates of hnRNPA2, MSI2, or CELF1 identified by CLIP-seq (Crosslinking and Immunoprecipitation followed by deep sequencing) in cancer cells." (PMID 38092740, 2023). "Notably, despite the structural resemblance between CELF family members, particularly between CELF1 and CELF2 (>90% similarity in their RNA-binding domains), their functions are quite different, notably in cancer." (PMID 34681716, 2021). "Moreover, a deregulated expression pattern of splice factors has been reported in CRC and in cancer generally, for instance, PTB1 and CELF1 have been reported to play a role in CRC proliferation." (PMID 33238574, 2020). "In addition, overexpressed CELF1 may account for alternative splicing of pre-mRNAs resulting in dominant negative isoforms and destabilization of pro-apoptotic mRNAs there by giving efficency to the cancer stem cells to create resistance for chemo/radiotherapy." (PMID 29728583, 2018). "Hence, in the absence of CELF1, the turnover of possible oncogenes could presumably decrease, consistent with the cancer cells showing decreased capacity of proliferation and colony formation." (PMID 24237593, 2013).
tumor (28 papers, 2013 to 2025). "In an inducible shRNA xenograft mouse model, we demonstrated that the loss of CELF1 expression resulted in reduced tumor burden." (PMID 26498364, 2015). "In vivo, combining CELF1 knockout with BAY-876 further curtailed tumor growth and proliferation markers." (PMID 41306913, 2025). "In vivo fluorescence imaging showed that stable knockdown of CELF1 significantly reduced fluorescence intensity compared to the NC group, indicating that CELF1 knockdown effectively increased tumor cell killing and sensitivity to ADR." (PMID 40781108, 2025). "Our mechanistic studies elucidate how tRF-24 drives tumor growth, metastasis and chemoresistance through CELF1 phase separation-mediated alternative splicing." (PMID 41250205, 2025). "It is likely that miRNA-mediated CELF1 inhibition has tumor suppressor effects; however, additional research is needed for different malignancies." (PMID 34681716, 2021). "Overexpression of circ_CELF1 impaired the tumor-suppressive effects induced by anti-PD-1 therapy, and a shorter survival time was observed in mice bearing circ_CELF1-expressing cells than mice with circ_NC-expressing cells." (PMID 34788230, 2021). "For example, Celf1 promotes expression of Cebpb via interacting with Eif2s1 and Eif2s2 in proliferating livers and in tumor cells." (PMID 32546682, 2020). "Together, these results expand the impact of our results to other pathologies, but also emphasize tumor-type selectivity in the regulation of CELF1 and DEK." (PMID 29269732, 2017). "Our analysis revealed that CELF1 expression was directly correlated to tumour stage and inversely correlated to tumour differentiation status, consistent with the notion that CELF1 expression is correlated to metastatic potential." (PMID 27869122, 2016). "Treatment of mice with 21mM IPTG in the drinking water led to a reduction in tumor volume for those cells stably transduced with inducible CELF1 shRNA in comparison to control cells, 1636mm3 and 3473mm3, respectively." (PMID 26498364, 2015). "To determine the role CELF1 protein expression plays in tumor growth, we injected inducible control shRNA (right-side) and CELF1 shRNA (left-side) UMSCC-74B clones into the flanks of nude mice." (PMID 26498364, 2015). "Suppression of CELF1 protein in vivo reduced tumor growth clearly demonstrating CELF1's role in tumor progression." (PMID 26498364, 2015). "Additionally, in the subsequent in vivo experiments of subcutaneous tumor implantation in nude mice, we also observed a substantial decrease in both tumor weight and volume in the CELF1-KO group." (PMID 41306913, 2025). "CELF1 expression was elevated in multiple tumor types, including AML." (PMID 40781108, 2025). "The alterations in CELF1 expression also impact the expressions of cyclin D1 and c-Myc, thereby implying a consequential modification in the occurrence, invasion, and metastasis processes within tumor tissues." (PMID 41306913, 2025). "Additionally, we found that knocking down CELF1 affects cellular autophagy levels, which is a critical factor in tumor drug resistance." (PMID 40781108, 2025). "Furthermore, we established an in vivo model system to validate CELF1’s regulatory role on ATG5-mediated autophagy as a tumor-suppressive mechanism." (PMID 40781108, 2025). "CELF1 can foster the migration and invasion of tumor cells by targeting ETS2 and other genes." (PMID 35126520, 2022). "The fact that the fusions STIP1-CREB3L1, ZDHHC5-GPR137, and CELF1-DDIAS were present in only four out of 12 tumors suggests that also additional fusions may characterize this tumor type." (PMID 28186972, 2017). "Whether this stabilizing function of CELF1 reflect tumor-specific protection against deadenylases or miRNAs63 deserves future attention." (PMID 29269732, 2017). "It will also be of interest in the future to investigate whether relative CELF1 protein expression is increased further in tumour invasive fronts, which have been shown to be enriched in migratory tumour stem cells." (PMID 27869122, 2016).